AFP (alpha fetoprotein)
Diseases named in the same sentence as AFP in open-access papers (continued):
Sharing a sentence is not in itself a finding about the gene and the disease.
tumor (continued). "We also observed a correlation between the MDM2 methylation and the gender, AFP, number of tumors, tumor size, vascular invasion and TNM stage, which means MDM2 methylation might take part in the development of HBV-related HCC." (PMID 40432974, 2025). "Combining decreased tumor stiffness and increased AFP levels may provide potential valuable biomarkers for Glypican-3 (GPC3)-targeted therapy and immunotherapy." (PMID 41160615, 2025). "Additionally, comprehensive combination analysis integrating anti-COPT1 autoantibodies with other conventional tumor markers (e.g., AFP, CA199, CA125) are recommended to enhance their clinical utility and diagnostic accuracy." (PMID 40292291, 2025). "Additionally, when combined with tumor markers such as AFP and des-gamma-carboxy prothrombin (DCP), the wd-score further improved diagnostic accuracy, yielding AUCs of 0.920 in the training set and 0.950 in the testing set." (PMID 40055844, 2025). "In Asia, where living donor liver transplantation (LDLT) predominates, the “5–5–500 rule” (tumors ≤ 5 cm in size, tumor number ≤ 5, and Alpha-fetoprotein: AFP level ≤ 500 ng/mL) has shown promising results in regional variations in organ availability have led to different transplantation approaches." (PMID 39907863, 2025). "In this group, the AFP level increased in seven patients, accounting for 58.3% (7/12) of patients, and decreased to normal after tumour resection, suggesting that the serum AFP level can be used as an indicator to evaluate the efficacy of PB and monitor recurrence." (PMID 40574954, 2025). "Additionally, blood tests showed elevated tumor markers, with a serum alpha-fetoprotein (AFP) level of 100 ng/mL and a protein induced by vitamin K absence-II (PIVKA-II) level of 938 mAU/mL, resulting in a diagnosis of HCC." (PMID 40438801, 2025). "Previous research has reported that small tumor size (< 5 cm), elevated alpha-fetoprotein (AFP, > 100 ng/mL), [18F]FDG positive lesions, positive circulating tumor cell status, and poorly demarcated gross types as single indicators favoring the selection of wide resection margin." (PMID 39235653, 2025). "The AFP-positive group demonstrated significantly more aggressive clinicopathological features, including larger tumor size (p < 0.05), deeper invasion (higher T-stage), increased lymph node metastasis (higher N-stage), and higher rates of distant metastasis (p = 0.035)." (PMID 40485723, 2025). "Besides tumor size and number, which are included in the Milan criteria, recent criteria included biomarkers such as AFP and tumor differentiation." (PMID 39941874, 2025). "circ_0009910 also correlates significantly with AFP, Size, TNM, and BCLC, indicating that it might be implicated in similar tumor progression pathways." (PMID 40429981, 2025). "Preoperative tumour markers were within normal limits: alpha-fetoprotein 1.4 ng/mL (reference range: 0.0-7 ng/mL), beta-human chorionic gonadotropin (β-hCG) 0.2 mIU/mL (reference range: 0.0-2.6 mIU/mL), and lactate dehydrogenase (LDH) 137 IU/L (reference range: 135-250 IU/L)." (PMID 41426877, 2025). "Elevated serum AFP, which correlates with tumor size, can aid in diagnosing PB." (PMID 40214914, 2025). "AFP is the most widely used and accepted serum tumor biomarker in HCC." (PMID 40221793, 2025). "Postoperative serum AFP level decreased to 7 ng/mL, indicating effective tumor clearance." (PMID 39706145, 2025). "Independent predictors for achieving TRG1(a&b) included male gender (OR = 3.44, P < 0.001), treatment with TACE combined with targeted therapy and immunotherapy (P < 0.001), pre-treatment tumor diameter of 5–10 cm (OR = 2.31, P = 0.012), and rapid normalization of AFP levels (OR = 0.97, P < 0.001)." (PMID 41246344, 2025).
tumor (continued). "Her tumor markers were notably reduced, with AFP 39 ng/mL and PIVKA-II 34 mAU/mL." (PMID 39980714, 2025). "Serum AFP dynamics and composite tumour markers refine candidacy: US allocation policy withholds an automatic exception when AFP > 1000 ng/mL unless it can be reduced and sustained < 500 ng/mL, reflecting aggressive biology and a higher risk of wait-list drop-out." (PMID 41301037, 2025). "Serum tumor markers commonly assessed include AFP, LDH, and β-hCG." (PMID 40755627, 2025). "In our study, AFP-positive patients exhibited significantly larger tumor sizes (5.90 ± 2.70 cm vs. 4.75 ± 2.30 cm, P = 0.032), supporting the hypothesis that AFP-positive tumors tend to be more aggressive." (PMID 40485723, 2025). "Eligibility is determined by a multidisciplinary tumour board, with decisions guided by treatment response, recurrence-free intervals, and both the reduction and sustained stability of AFP levels—closely aligning with the downstaging principles outlined in the UNOS-DS criteria." (PMID 40647548, 2025). "The final scores were determined as follows: non‐smooth tumor margin (2 points), ill‐defined capsule (2 points), presence of peritumoral star node (2 points), AFP > 400 (1 point), Radscore [0, 4.84] (2 points), [4.84, 5.81] (3 points), [5.81, 6.38] (5 points), and (6.38, maximum value) (6 points)." (PMID 39964132, 2025). "In addition to AFP, tumor stage, vascular infiltration, age, and other common prognostic risk factors, increasing number of genetic signatures have been added to build the nomogram model for HCC50." (PMID 39972122, 2025). "Furthermore, Hep G2 tumor-bearing NSG mice that receive intravenous AFP-CAR T-cell injection have a significant and quick suppression of tumor development (n = 6)." (PMID 40098955, 2025). "Therefore, we devised a simple score for forecasting prognosis based on these two variables, named ATSI (AFP and Tumor Shape Irregularity)." (PMID 39714631, 2025). "Tumor markers included elevated AFP 57.2 ng/mL, AFP-L3 11.5%, DCP 261mAU/mL." (PMID 39446307, 2025). "The low AFP expression group had a larger tumor size than the high AFP expression group." (PMID 39488822, 2025). "In the training set, univariate logistic regression analysis revealed that patients with positive MVI status were more likely to have an alpha-fetoprotein (AFP) level greater than 200 ng/mL (odds ratio [OR] = 1.98, p = 0.01) and a tumor diameter greater than 5 cm (OR = 1.92, p = 0.01)." (PMID 40610844, 2025). "Tumor markers, including CA-125, CA 19-9, and alpha-fetoprotein (AFP), were within normal limits." (PMID 40895704, 2025). "Immunophenotypically, the tumor cells are positive for alpha-fetoprotein (AFP) and glypican-3." (PMID 40900781, 2025). "We found that ATR was more effective in predicting OS and RFS than AFP or tumor size alone." (PMID 40857604, 2025). "Laboratory investigations showed elevated tumor markers (AFP 95.4 ng/mL, CEA 2183 ng/mL, CA15.3–55 U/mL, CA125–418 U/mL, and CA19.9–400 U/mL), while platelet count, white cell count, electrolytes, liver and renal function tests, and coagulation profile were within normal limits." (PMID 41409243, 2025). "Laboratory tests showed markedly elevated tumor markers: alpha-fetoprotein (AFP) >1210 ng/mL (reference level <10 ng/mL), carcinoembryonic antigen (CEA) 15.32 ng/mL (reference level <5 ng/mL), and beta-human chorionic gonadotropin (β-HCG) <0.10 mIU/mL (reference level <1 mIU/mL)." (PMID 41235014, 2025). "Numerous tumour markers are currently employed in clinical diagnostics, including proteins (such as alpha-fetoprotein (AFP), phosphatidylinositol glycoprotein-3 (GPC-3), prostate-specific antigen (PSA), and carbohydrate antigens), nucleic acids, and other biomolecules." (PMID 41013140, 2025). "Elevated AFP levels in GC may reflect both the tumor’s biological behavior and its interaction with the liver." (PMID 40485723, 2025).
tumor (continued). "This tumor may secrete AFP and/or β-hCG in up to 60% of cases, which may induce endocrine malfunction, causing precocious puberty or menstrual abnormalities." (PMID 40723200, 2025). "Serum tumor markers, including cancer-associated antigen 19-9, carcinoembryonic antigen, alpha-fetoprotein, and beta-human chorionic gonadotropin, showed no elevation." (PMID 40388736, 2025). "In a 125-patient real-world HCC analysis using a tumour-informed assay, serial ctDNA monitoring detected recurrence earlier than AFP, with a median lead time ~7.9 months in subcohorts (post-resection and post-LT) and clear prognostic separation by ctDNA status." (PMID 41301037, 2025). "Tumor markers such as AFP, CEA, and CA 15-3 can be detected in ISF." (PMID 40723883, 2025). "This study aimed to compare the levels of tumor markers, specifically alpha-fetoprotein (AFP), carbohydrate antigen 19-9 (CA 19-9), carcinoembryonic antigen (CEA), and prostate-specific antigen (PSA), between combustible cigarette (CC) smokers, any HTP users, and quitters." (PMID 40078230, 2025). "Elevated tumor-marker levels were noted, with AFP at 45.9 ng/mL and PIVKA-II at 121 mAU/mL." (PMID 41450371, 2025). "On subsequent multivariate Cox regression analysis, serum AFP level (hazard ratio (HR) = 1.4; 95% CI: 1.0, 1.9; p = 0.05), tumor multiplicity (HR = 1.8; 95% CI: 1.2, 2.6; p = 0.003) and TTB (HR = 2.2; 95% CI: 1.6, 3.0; p < 0.001) were found to be predictive of ER." (PMID 39028376, 2025). "Tumor markers showed a significant decrease, with AFP reduced to 153.5 ng/mL and DCP to 222 AU/mL." (PMID 40500480, 2025). "AFP staining was strongly positive, indicating that the tumor produced AFP." (PMID 40406259, 2025). "We found that increased STK25 expression in the livers of individuals with HCC was associated with the upregulated concentration of serum α-fetoprotein (AFP; a biomarker of a cancer-permissive tissue milieu) as well as advanced histologic grade and pathologic stage of the tumor." (PMID 40024534, 2025). "We found that patients with lower AFP levels and smaller tumors exhibited better response rates and liver function preservation, aligning with findings suggested that the significance of stratifying patients based on liver function and tumor burden." (PMID 40308490, 2025). "Regression of malignant changes; ↓ AST/ALT/γ-GT and AFP (tumour activity marker)." (PMID 41471707, 2025). "Additionally, IL-10 positively correlated with poorer Child-Pugh score (r = 0.187, p<0.05), and serum levels of tumor markers, including AFP (r = 0.208, p<0.05) and protein induced by vitamin K absence-II (PIVKA-II) (r = 0.227, p<0.05)." (PMID 40568585, 2025). "Based on clinical symptoms, serum tumor markers—AFP, CA199, and LDH—were assessed." (PMID 41018086, 2025). "Tumor serum markers, including alpha-fetoprotein (AFP), beta-human chorionic gonadotropin (β-hCG), and lactate dehydrogenase (LDH), may hint at TGCT subtypes pre-operatively but have low sensitivity (SEN)." (PMID 40750949, 2025). "Future studies could design large-scale cohort studies to assess the diagnostic value of combining NLRP3 inflammasome levels with classic tumor biomarkers such as AFP and CA-125." (PMID 40718836, 2025). "The most commonly increased tumor markers are alpha-fetoprotein, β-hCG, and lactate dehydrogenase." (PMID 41209905, 2025). "While classical tumor markers remained essential in diagnosis and staging, the integration of inflammatory indices provided additional discriminatory power, especially in patients with normal or equivocal AFP and hCG values." (PMID 41283275, 2025).
tumor (continued). "Notably, AFP levels have been associated with MVI, macrovascular invasion, and poor tumor differentiation." (PMID 40857604, 2025). "The PDP of the RSF model showed that unfavorable clinical factors, including a high AFP, Child–Pugh B, the presence of PVTT or metastasis, advanced BCLC stage, a large tumor size, and an elevated AST, were consistently associated with poorer survival probabilities." (PMID 41267980, 2025). "Aspartate aminotransferase (AST), alanine aminotransferase (ALT), and alpha-fetoprotein (AFP), reflect liver damage and tumor biological characteristics from distinct perspectives; however, there may be a high correlation among them." (PMID 41142312, 2025). "Current evidence indicates a relationship with tumor dedifferentiation, during which tumor cells may aberrantly reactivate fetal gene expression programs and acquire the capacity to synthesize AFP." (PMID 41293148, 2025). "While postoperative AFP trends offer insights into recurrence risk, these data do not fully reflect the patient’s background or initial tumor characteristics." (PMID 40238062, 2025). "Given this relationship, AFP and tumor size may exert a combined effect on HCC prognosis, warranting further investigation into their joint prognostic value." (PMID 40857604, 2025). "Sustained, and specifically, increased AFP expression in patients with an apparent CR may trigger a thorough tumor board review and include transarterial angiography to identify other sources of tumor-feeding vessels or investigate indeterminate observations." (PMID 41137977, 2025). "The top 3 important features were tumor diameter, timing of hepatectomy, and AFP level." (PMID 39832130, 2025). "In addition, we explored survival outcomes among high-risk patients who did not undergo fast-track LDLT, stratified by a composite definition of tumor progression, integrating both radiological response and AFP kinetics." (PMID 40361345, 2025). "DCP and AFP levels increased in patients with tumor progression." (PMID 40940925, 2025). "This additional staining demonstrated AFP positivity in a portion of the tumor cells." (PMID 41561743, 2025). "Furthermore, consistent with previous research, the LASSO-selected features and multivariate logistic regression confirmed tumor diameter, AFP, GGT, and the differentiation grade as significant predictors of HCC MVI/Ki-67 dual positivity." (PMID 41237121, 2025). "Follow-up protocols as per the European Guidelines include regular clinical examinations and tumor marker assessments (AFP, β-hCG, and LDH) at defined intervals - every three months during year 1, every four months in year 2, every six months until year 5, and annually thereafter." (PMID 40755627, 2025). "Similarly, in a multicentric European–Asiatic experience, AFP combined with tumor morphology formed the Metroticket 2.0 score, which was strongly associated with HCC-specific death (c-statistic = 0.78, 95%CI = 0.76–0.80; p < 0.001)." (PMID 40361345, 2025). "Notably, AFP levels were significantly correlated with clinical indicators of cancer progression, including advanced tumor stage and lymph node metastasis." (PMID 40430002, 2025). "Tumor markers such as AFP, CEA, and CA 19-9 were assessed in selected cases, with variable results." (PMID 41156201, 2025). "The results indicated a significant negative correlation between the tumor size reduction rate and AFP decline ratio during conversion therapy, and the risk of recurrence within one year after surgery." (PMID 40934000, 2025). "Additionally, tumor markers including alpha-fetoprotein (AFP), beta-human chorionic gonadotropin (B-HCG), and CA125 were measured, all of which were found to be within normal ranges." (PMID 39839690, 2025). "An increase or sustained elevation of AFP levels after treatment may indicate treatment failure or tumor recurrence." (PMID 40430002, 2025). "AFP levels went down to 132 ng/ml, and the tumor burden was decreased." (PMID 41510478, 2025).
tumor (continued). "Notably, elevated serum levels of tumor markers such as β-human chorionic gonadotropin (β-hCG) or alpha-fetoprotein (AFP) indicate the presence of other co-existing GCT components rather than being caused by the teratomatous elements themselves." (PMID 40697355, 2025). "Persistently high AFP levels post-procedure may indicate incomplete tumor necrosis or early recurrence." (PMID 40308490, 2025). "Tumor cell positivity for glypican-3 and AFP supported yolk sac differentiation." (PMID 41510478, 2025). "However, the tumor markers measured immediately before starting therapy were markedly reduced (AFP, 361 ng/mL; DCP, 47 mAU/mL) (53 days after the first visit)." (PMID 40696641, 2025). "Future studies should therefore extend this bead-based approach by incorporating analyses of tumor-specific mutations or methylation patterns within HCC-related genes in cfDNA, or by evaluating additional protein markers (e.g., GPC3) in CTCs alongside AFP." (PMID 41002319, 2025). "They found that ctDNA levels correlated with tumor burden, macroscopic residual disease, and treatment response, underscoring its utility as a non-invasive tool for monitoring HB progression alongside traditional markers like AFP." (PMID 40136353, 2025). "However, AFP levels were significantly higher in the GPC3-positive group, consistent with the association between GPC3 expression and elevated tumor marker burden." (PMID 41463223, 2025). "S1 shows aberrant WNT/TGF-β activation and greater early recurrence, S2 is a proliferation phenotype [MYC/protein kinase B (AKT) targets] with larger tumours and higher serum AFP, and S3 is a hepatocyte-differentiated phenotype with lower AFP and better differentiation." (PMID 41301037, 2025). "The risk scores increased significantly with the progression of the clinical T-stage, pathological stage, pathological grading, tumor free (the patient was tumor-free up to the follow-up cut-off time), the levels of alpha-fetoprotein, fibrosis Ishak score, and the status of vascular invasion." (PMID 40735692, 2025). "They found AFP level, tumor size, and radionics score as independent predictors of MVI." (PMID 39941874, 2025). "Furthermore, our study mainly focused on preoperative imaging features and their correlation with tumor grading, without incorporating clinical variables like patient age, tumor size, or serum tumor markers like AFP." (PMID 40597816, 2025). "In this regard, a recent work has reported a correlation between the expression ratio of the main TGCT serum markers, including AFP, compared to the volume of the tumor mass, to verify the relationship of their expression with the survival of patients without recurrence." (PMID 40723290, 2025). "Since it has components of both HCC and ICC, theoretically, tumor markers AFP and PIVKA II for HCC and CA19–9 and CEA for ICC could be used." (PMID 40589631, 2025). "In addition to physical examination and imaging, a key point for TGCT diagnosis and management is the analysis of serum tumor markers, including alpha-fetoprotein (AFP), beta-human chorionic gonadotropin (hCGβ), and lactate dehydrogenase (LDH)." (PMID 40723290, 2025). "We chose four criteria for our study: the Milan and UCSF criteria, due to their long-standing international recognition and comparability with global studies; and the Metro-Ticket 2.0 model and Hangzhou criteria, which include AFP thresholds for tumor specificity." (PMID 40962936, 2025). "Furthermore, our study solely focused on analyzing the appearance of tumor morphology and enhancement; in contrast, the utilization and analysis merger of laboratory tests (AFP, PIVKA-II) in predicting MVI grades were weakly relevant." (PMID 40214224, 2025). "In HCC with elevated tumor markers, the dynamic change of AFP at 3 months after EBRT and MoRAL score at 3 months after EBRT could be recommended as potential indicators." (PMID 40392828, 2025).